LINC01173 (long independently transcribed non-coding RNA 1173)
Synonyms: TCONS_00004057
Gene: Long non-coding RNA gene on chromosome 2 (234,682,333 to 234,723,480, forward strand). Ensembl gene ENSG00000280744.
Diseases named in the same sentence as LINC01173 in open-access papers:
LINC01173 is named in the same sentence as 3 diseases in open-access papers, as found by Europe PMC text mining. Sharing a sentence is not in itself a finding about the gene and the disease. The quoted sentences say what the papers report.
adenoma (1 paper, 2020). A neoplasm arising from the epithelium. "Finally, TSH adenomas showed 68 genes that could be regulated by methylation including SSTR2, GRIA2 and LINC01173." (PMID 33168897, 2020).
LINC01173 also shares sentences with these, for which no sentence is quoted: cancer (1 paper); tumour (1).